CDC73 (cell division cycle 73)
Description:
Tumor suppressor probably involved in transcriptional and post-transcriptional control pathways. May be involved in cell cycle progression through the regulation of cyclin D1/PRAD1 expression. Component of the PAF1 complex (PAF1C) which has multiple functions during transcription by RNA polymerase II and is implicated in regulation of development and maintenance of embryonic stem cell pluripotency. PAF1C associates with RNA polymerase II through interaction with POLR2A CTD non-phosphorylated and 'Ser-2'- and 'Ser-5'-phosphorylated forms and is involved in transcriptional elongation, acting both independently and synergistically with TCEA1 and in cooperation with the DSIF complex and HTATSF1. PAF1C is required for transcription of Hox and Wnt target genes. PAF1C is involved in hematopoiesis and stimulates transcriptional activity of KMT2A/MLL1; it promotes leukemogenesis through association with KMT2A/MLL1-rearranged oncoproteins, such as KMT2A/MLL1-MLLT3/AF9 and KMT2A/MLL1-MLLT1/ENL. PAF1C is involved in histone modifications such as ubiquitination of histone H2B and methylation on histone H3 'Lys-4' (H3K4me3). PAF1C recruits the RNF20/40 E3 ubiquitin-protein ligase complex and the E2 enzyme UBE2A or UBE2B to chromatin which mediate monoubiquitination of 'Lys-120' of histone H2B (H2BK120ub1); UB2A/B-mediated H2B ubiquitination is proposed to be coupled to transcription. PAF1C is involved in mRNA 3' end formation probably through association with cleavage and poly(A) factors. In case of infection by influenza A strain H3N2, PAF1C associates with viral NS1 protein, thereby regulating gene transcription. Connects PAF1C with the cleavage and polyadenylation specificity factor (CPSF) complex and the cleavage stimulation factor (CSTF) complex, and with Wnt signaling. Involved in polyadenylation of mRNA precursors.
Synonyms: C1orf28; HRPT2; parafibromin; FIHP; HPTJT; HRPT1; HYX
Tractability: PROTAC: UniProt records ubiquitination sites on it; ubiquitination databases record sites on it; its protein half-life has been measured.
Gene: Protein-coding gene on chromosome 1 (193,115,732 to 193,264,613, forward strand). Ensembl gene ENSG00000134371.
Subcellular location: Nucleus
Subcellular location (Human Protein Atlas): Nucleoplasm; Cytosol
Pathways (Reactome):
Gene expression (Transcription): Formation of RNA Pol II elongation complex; RNA Polymerase II Pre-transcription Events; RNA Polymerase II Transcription Elongation
Signal Transduction: Formation of the beta-catenin:TCF transactivating complex; Hedgehog 'on' state
Chromatin organization: CHD1 and CHD2 subfamily
Disease: Dengue virus activates/modulates innate and adaptive immune responses
Metabolism of proteins: E3 ubiquitin ligases ubiquitinate target proteins
Gene Ontology:
Molecular function: protein binding; RNA polymerase II complex binding
Biological process: mRNA 3'-end processing; negative regulation of cell population proliferation; negative regulation of epithelial cell proliferation; negative regulation of fibroblast proliferation; negative regulation of G1/S transition of mitotic cell cycle; negative regulation of myeloid cell differentiation; negative regulation of transcription by RNA polymerase II; positive regulation of cell cycle G1/S phase transition; positive regulation of mRNA 3'-end processing; positive regulation of transcription by RNA polymerase II; positive regulation of Wnt signaling pathway; protein destabilization; transcription elongation by RNA polymerase II; cellular response to lipopolysaccharide; endodermal cell fate commitment; positive regulation of transcription elongation by RNA polymerase II; stem cell population maintenance
Cellular component: Cdc73/Paf1 complex; chromosome, telomeric region; nucleoplasm; nucleus
Genetic constraint (gnomAD): Loss-of-function variants: 9 observed, 37.36 expected, observed/expected ratio (o/e) 0.24, 90% interval 0.14 to 0.42. The upper end of that interval is the gene's LOEUF score, 0.42, which puts it in group 1 of 6, group 1 being the genes least tolerant of losing a copy. Missense variants: 162 observed, 329.49 expected, observed/expected ratio (o/e) 0.49, 90% interval 0.43 to 0.56. Synonymous variants: 102 observed, 111.71 expected, observed/expected ratio (o/e) 0.91, 90% interval 0.78 to 1.08.
Gene-disease validity (ClinGen):
ClinGen rates the evidence that CDC73 causes each of these diseases.
hyperparathyroidism 2 with jaw tumors (autosomal dominant): Definitive. An autosomal dominant inherited syndrome characterized by the development of parathyroid adenoma or carcinoma, ossifying fibroma of the mandible and maxilla, renal neoplasms, and renal cysts.
Cancer hallmarks: escaping programmed cell death (promotes); invasion and metastasis (suppresses); suppression of growth (promotes)
Homologues: Orthologues: chimpanzee CDC73 (100% identical), macaque CDC73 (100% identical), mouse Cdc73 (100% identical), pig CDC73 (100% identical), rat Cdc73 (100% identical), tropical clawed frog cdc73 (94% identical), rabbit CDC73 (94% identical), zebrafish cdc73 (91% identical), guinea pig CDC73 (80% identical), Caenorhabditis elegans cdc-73 (29% identical), Drosophila melanogaster CG6220 (22% identical).
Diseases named in the same sentence as CDC73 in open-access papers:
CDC73 is named in the same sentence as 111 diseases in open-access papers, as found by Europe PMC text mining. Sharing a sentence is not in itself a finding about the gene and the disease. The quoted sentences say what the papers report.
parathyroid carcinoma (62 papers, 2008 to 2026). "Mutations in the tumor suppressor gene CDC73 represent one of the essential molecular mechanisms about the onset of parathyroid carcinoma." (PMID 40038693, 2025). "In parathyroid cancer, CDC73 is a tumor suppressor gene, and variant of CDC73 is related to risk of parathyroid carcinoma." (PMID 41318472, 2025). "Individuals with the disorder carry a CDC73 gene mutation that predisposes them to early-onset primary hyperparathyroidism, ossifying jaw tumours, renal cystic disease, uterine tumours and parathyroid carcinomas." (PMID 39839692, 2025). "Up to 70% of sporadic parathyroid carcinomas demonstrate CDC73 mutations (compared to 2% of parathyroid adenomas)." (PMID 40530390, 2025). "CDC73 pathogenic variants are also associated with a higherfrequency of parathyroid carcinoma, as observed in our index case." (PMID 40893023, 2025). "In patients with parathyroid cancer, the presence of a CDC73 mutation and parafibromin loss has been associated with a low survival rate at 10-year follow-up." (PMID 40434298, 2025). "High-impact germline CDC73 mutations have been demonstrated to enhance the incidence of parathyroid cancer via altering the C-terminal domain(CTD) of parafibromin." (PMID 38884084, 2024). "The increased incidence of this neoplasia in HJT is probably related to CDC73 gene; notably, some of its pathogenic variants have been reported in up to 75% of the sporadic parathyroid malignant tumours, as well (outside HJT)." (PMID 38396977, 2024). "First aspect being only 8 cases have been reported in literature regarding parathyroid carcinoma in pregnancy and secondly, identified frameshift mutation of CDC73 gene is a novel variant." (PMID 36284286, 2022). "Somatic mutations of CDC73 have been found in a significant fraction of sporadic parathyroid tumours: 60–90.9% of parathyroid carcinomas and up to 6% of parathyroid adenomas harbour CDC73 mutation." (PMID 35805976, 2022). "Mutations of CDC73/HRPT2 have been reported in only 60–90.9% of parathyroid carcinoma and 1–6% of adenomas." (PMID 35805976, 2022). "It has been estimated that 20–30% of apparently sporadic parathyroid carcinomas are associated with germline CDC73/HRPT2 mutation." (PMID 35805976, 2022). "One patient with a WT1 variant (c.1139G>A [p.Arg380Gln]), reported as VUS, had a pathogenic CDC73 mutation (c.376C>T [p.Arg126Ter]) and was diagnosed with parathyroid cancer." (PMID 35586626, 2022). "Loss or mutation of CDC73 (cell division cycle 73) found in parathyroid carcinoma was reported to disrupt physical interactions between the PAF1 complex and RNF20/40 and thus lead to loss of H2Bub1." (PMID 33199825, 2021). "In a recently published whole-genome sequencing study of 23 parathyroid carcinomas, the authors conclude that CDC73 gene mutations were the most common sequence aberration, occurring in almost 40% of cases." (PMID 33269427, 2021). "The hyperparathyroidism in HPT-JT syndrome is usually associated with a parathyroid adenoma; however, 15–40% of patients carrying CDC73 mutations or gene deletions will develop parathyroid carcinoma." (PMID 33269427, 2021). "Increased copy number variants were seen in parathyroid carcinomas with CDC73 mutations, and these cases also carried an increased tumor mutational burden and poorer patient outcome." (PMID 33269427, 2021). "A genotype-phenotype correlation has been observed among CDC73-mutation carriers such that those with frameshift, nonsense or deletion mutations are nearly 7-fold more likely to develop parathyroid cancer than patients harboring missense CDC73 mutations." (PMID 33716975, 2021). "Mutations of CDC73 also cause CDC73-related isolated familial hyperparathyroidism and CDC73-related parathyroid carcinoma." (PMID 32326947, 2020).
parathyroid carcinoma (continued). "Somatic mutations in CDC73 in humans are associated with breast, renal, gastric, and parathyroid cancers, and germline mutations in CDC73 cause the cancer susceptibility syndrome hyperparathyroidism-jaw tumor syndrome (HPT-JT)." (PMID 29320491, 2018). "The majority of the CDC73 gene loss-of-function mutations associated with hyperparathyroidism and parathyroid carcinoma are frame-shift, nonsense or missense occurring within the protein-encoding exons." (PMID 28774260, 2017). "Mutations in CDC73 have also been frequently detected in sporadic parathyroid carcinomas and renal tumors." (PMID 27658992, 2016). "In summary, we report a previously unreported intragenic deletion involving exons 1–10 of the CDC73 gene in familial PHPT associated with parathyroid carcinoma." (PMID 24823466, 2014). "Further studies are needed to evaluate the predictive value of these tumor markers (17, 19, –, 21) in patients with CDC73 germline mutations in sporadic cases of parathyroid carcinomas and atypical adenomas." (PMID 24823466, 2014). "In contrast, mutations of CDC73 are frequently seen in apparently sporadic cases of parathyroid carcinoma." (PMID 25177504, 2014). "Inactivating mutations of the CDC73 tumor suppressor gene have been reported in parathyroid carcinomas (PC), in association with the loss of nuclear expression of the encoded protein, parafibromin." (PMID 24145611, 2013). "Another example is human CDC73 (also known as HRPT2; encodes “parafibromin”), in which mutations lead to parathyroid cancer." (PMID 23613755, 2013). "The present study supplies information on the mutations and protein expression of HRPT2/CDC73 gene and phenotypes of parathyroid carcinoma in Chinese population." (PMID 23029104, 2012). "CDC73 gene mutations are exceedingly rare in sporadic parathyroid adenomas, but are more commonly found in cases of sporadic parathyroid carcinomas and in parathyroid tumors from patients with the HPT-JT syndrome, both infrequent conditions." (PMID 23029479, 2012). "Given the strong evidence linking inactivation of HRPT2/CDC73 gene and malignant parathyroid tumor, gene mutations screening and detection of parafibromin immunoreactivity have been suggested as diagnostic instruments of PC." (PMID 23029104, 2012). "Genetic testing for germline CDC73 pathogenic variants is appropriate in most patients with sporadic parathyroid carcinoma, particularly when there are family members who may benefit from genetic counseling." (PMID 41568161, 2026). "Somatic and germline CDC73 variants are identified in a high proportion of patients with parathyroid carcinoma, with some estimates suggesting CDC73 mutation in two-thirds of all parathyroid carcinoma cases." (PMID 39677927, 2025). "Screening for CDC73-related disorders has high clinical value because of the risk for parathyroid carcinoma, tumors of the kidney and uterus that may also be malignant, and the potential for locally aggressive jaw tumors." (PMID 39677927, 2025). "The CDC73 mutation carriers demand particular attention due to a substantially increased lifetime risk of parathyroid carcinoma (15-20% in adults), warranting a low threshold for en-bloc resection if malignancy is suspected and necessitating long-term vigilance." (PMID 41210508, 2025). "In addition, the tumor of patient 9 stained positive for WT1, a novel IHC marker for CDC73-mutated parathyroid cancer as suggested in our previous study." (PMID 40434298, 2025). "In some families up to 85% of carriers suffered from a parathyroid carcinoma thus indicating that certain CDC73 pathogenic variants may harbour a higher risk." (PMID 38396977, 2024). "The syndromic forms of PHPT are due to LOF of tumor suppressor genes, e.g., MEN1, CDKN1B, and CDC73, with patients harboring germline CDC73 mutations having a higher occurrence of parathyroid carcinomas or increased oncogenic signaling (e.g., activating RET mutations)." (PMID 38038882, 2024).
parathyroid carcinoma (continued). "Importantly, parathyroid carcinoma is over-represented in patients with CDC73 germline or somatic mutations, which suggests that parafibromin plays an important tumor suppressor role in the parathyroid gland." (PMID 38038882, 2024). "This case shows the importance of stringent follow up of atypical parathyroid adenoma patients, the benefit of second trimester surgery in management of hypercalcemia due to parathyroid carcinoma during pregnancy and the importance of identifying the novel CDC73 gene mutation." (PMID 36284286, 2022). "We included 13 patients with parathyroid cancer, and three of them had CDC73 mutations." (PMID 35586626, 2022). "Pathogenic CDC73 mutation is suspected to cause parathyroid cancer, and the WT1 variant could be an incidental finding from NGS." (PMID 35586626, 2022). "Somatic CDC73 gene mutations are the most frequent somatic alteration in parathyroid carcinoma." (PMID 33269427, 2021). "In apparently sporadic cases of parathyroid cancer, mutations of CDC73 are frequently identified." (PMID 33716975, 2021). "Furthermore, loss of parafibromin expression and the finding of inactivating CDC73 DNA variants can be found in aggressively behaving parathyroid cancers, and as such provide prognostic information." (PMID 31176307, 2019). "Moreover, the CDC73 gene is implicated in sporadic parathyroid carcinomas and mutations are present in up to 70% of cases." (PMID 28774260, 2017). "Patients presenting with apparently sporadic parathyroid carcinomas may carry germline mutations in the CDC73 gene, and may thus have the potential to express the HPT-JT syndrome or a variant." (PMID 28774260, 2017). "The presence of a CDC73 mutation is associated with increased risk of parathyroid carcinoma." (PMID 28774260, 2017). "Clinical characteristics and HRPT2/CDC73 mutations in patients of parathyroid carcinoma." (PMID 23029104, 2012). "Moreover, somatic CDC73 gene mutations are found in the majority of sporadic parathyroid carcinomas, an entity which is over-represented in the HPT-JT syndrome." (PMID 23029479, 2012). "Mutations of HRPT2/CDC73 gene in patients with parathyroid carcinoma." (PMID 23029104, 2012). "As CDC73 mutations may underlie both benign and malignant parathyroid tumors with varying penetrance and phenotypes, one can, therefore, speculate that mutations of the PRUNE2 gene could also give rise to similarly varying parathyroid tumor phenotypes with similarly varying penetrance." (PMID 36900197, 2023). "Interestingly, germline loss-of-function mutation in CDC73 may be found in some 25% of patients with seemingly sporadic parathyroid carcinoma, suggesting that such patients may have either de novo germline mutation in CDC73 or else a forme fruste of HPT-JT." (PMID 33716975, 2021). "Also, somatic mutation of CDC73 gene is present in 60–100% of sporadic parathyroid carcinoma." (PMID 25177504, 2014). "Approximately 1% are parathyroid carcinomas, associated with inactivation of the CDC73/HRPT2 double allele, RET mutations, and in some cases HPT-JT or MEN1 syndrome." (PMID 41210508, 2025). "While the truncating somatic variant detected in our patient has been reported solely in parathyroid carcinoma (N = 4) in the COSMIC database, other somatic variants in CDC73 are reported in 2% (30/1679) of soft tissue tumors." (PMID 39594770, 2024). "We tested the feasibility of using WT1 as a single-gene biomarker for CDC73-mutant parathyroid carcinoma." (PMID 37121965, 2023). "Conversely, the inactivation of the tumor suppressor gene CDC73 has been found to be a crucial determinant in the carcinogenesis of parathyroid carcinoma, with a prevalence of up to 70% in sporadic cases." (PMID 37854190, 2023).